CD47 (CD47 molecule)
Diseases named in the same sentence as CD47 in open-access papers (continued):
Sharing a sentence is not in itself a finding about the gene and the disease.
tumor (continued). "In the current investigation, it was observed that administration of anti-CD47 treatment resulted in an elevation in microvessel density within the tumor." (PMID 38532108, 2024). "The full‐length SLAMF7 protein and CD47 nanobody were initially designed to construct a fusion protein targeting tumor cells." (PMID 39713206, 2024). "IGF-1 and CCL20 promote tumour progression, while SIRPα interacts with CD47 expressed on tumour cells to inhibit microglial phagocytosis." (PMID 39364322, 2024). "CD38/CD47 BsAbs (IMM5605) can inhibit tumor growth via ADCC and ADCP in xenograft CB17-SICD mouse models." (PMID 38983860, 2024). "While anti-PD-1 and anti-CD47 combination therapy shows shrinking of tumor masses, further research is required to understand the changes in interactions between DC, T cell, and macrophage populations." (PMID 38261139, 2024). "Expectedly, the addition of CD47 nanobody to the PTT regimen significantly suppressed tumor development; all tumors in this group were eradicated and did not regrow until the end of the experiment (60 days)." (PMID 38888519, 2024). "While comparing between matched and unmatched tumour and normal tissue samples, upregulation of checkpoint receptor genes, notably CD47, CTLA4, HAVCR2, PVRIG, SIGLEC7, and SIGLEC9, were specifically detected in malignant compared to normal tissues." (PMID 39877370, 2024). "As an important tumor antigen that affects the onset and progression of various cancers, CD47 interacts with SIRPα to release a certain signal to escape phagocytosis." (PMID 39169402, 2024). "Blocking CD47 not only directly enhances the ability of macrophages to engulf tumor cells, but also activates effector T cells and strengthens the adaptive immune response by facilitating the presentation of tumor antigens on macrophages." (PMID 38532108, 2024). "Researchers have observed that even after inhibiting the expression of CD47, certain tumor cells can still evade macrophage phagocytosis." (PMID 38273373, 2024). "One such mechanism is the expression of CD47 in tumor cells, which sends a “don’t eat me” signal to macrophages and thus prevents phagocytosis." (PMID 39201801, 2024). "Previous studies in various preclinical models have demonstrated that blocking the CD47-SIRPα pathway can enhance phagocytic functions, demonstrating significant anti-tumor efficacy across multiple tumor types." (PMID 38650924, 2024). "The high expression of CD47 was positively correlated with histological type (p = 0.007) and tumor grade (p = 0.002)." (PMID 38832992, 2024). "High levels of CD47 form a more permissive microenvironment that allows tumor evasion from innate immunity attack." (PMID 38247566, 2024). "For example, the anti-CD47 antibody magrolimab induces tumor phagocytosis and eliminates leukemic stem cells." (PMID 38459166, 2024). "Engagement of SIRPα with CD47 on myeloid cells contributes to the generation of an immune-suppressive environment by reducing sampling, processing, and presentation of tumor-derived antigen to infiltrating T cells." (PMID 38577107, 2024). "Weak cell membrane staining of CD47 and strong CD47 staining on neurites of the favorable tumor cells were observed." (PMID 38920727, 2024). "Research on lung and breast cancers has shown that antibody–drug conjugates (ADCs) developed against CD47 can inhibit tumor growth and eliminate radioresistant cells." (PMID 39682556, 2024). "CD47, serving as an intrinsic immune checkpoint, has demonstrated efficacy as an anti-tumor target in hematologic malignancies." (PMID 38532108, 2024). "CD47 expressed on the surface of tumor cells binds to SIRPα on the surface of macrophages, leading to phosphorylation of the immune receptor tyrosine inhibitory motif (ITIM) in the intracellular domain of SIRPα." (PMID 38429732, 2024).
tumor (continued). "Based on this background, we performed proof-of-principle studies that revealed that targeting lactate generation in combination with anti-CD47 therapy augments antitumor immune responses and inhibits tumor growth." (PMID 39545414, 2024). "By elucidating the cell-intrinsic mechanisms regulated by CD47, we gain insights into its role in promoting tumor biology." (PMID 38720108, 2024). "The two remaining mice show significantly slower tumor growth than naïve mice challenged with regular B16F10 CD47 KO (median survival of 14 days) and can be considered partial responders." (PMID 38805560, 2024). "Immuno-tumoroids of MPS1i-treated B16F10 CD47 KO cells show macrophages with M1-like, anti-tumor markers and reduced expression of M2-like, pro-tumoral markers." (PMID 38805560, 2024). "On the contrary, living tumor cells have developed strategies to elude phagocytosis by TAMs through the extensive expression of anti-phagocytic molecules such as CD47." (PMID 39691192, 2024). "The data collectively indicate that the concurrent utilization of angiogenetic axis blockade and CD47/SIRPα axis inhibition can effectively stimulate both the innate and adaptive immune systems, resulting in a synergistic anti-tumor response." (PMID 38532108, 2024). "Given our results demonstrating the role of CD8+ T cells in CD47 × PD‐L1 BisAb‐mediated tumor control, we assessed the advantage of combined CD47 and PD‐L1 blockade over anti‐PD‐L1 monotherapy." (PMID 39584189, 2024). "Clinical significance of these findings has been translated into the development of therapeutic compounds blocking CD47 interaction with SIRPα in order to reinvigorate anti-tumor immune responses, with some of them reaching Phase I and II human trials." (PMID 39742254, 2024). "And indeed, there is such a relationship as infiltration by numerous CD68-IT cells was much more frequent among patients with a high expression of CD47 in tumor cells (p = 0.006)." (PMID 39201801, 2024). "The upregulated CD47 in tumor cells interacts with SIRPα, which is prominently expressed on the surface of myeloid cells, triggering “don’t eat me” signals." (PMID 38398223, 2024). "For CD47, 49 patients (70%) had high levels, 19 patients (27%) had medium levels and 2 patients (3%) had low levels in their tumor cells." (PMID 39627379, 2024). "In summary, in the current study, we provide preclinical evidence that CD47 blockade combined with chemotherapy significantly enhanced macrophage phagocytosis of ES cells in vitro and significantly decreased ES xenograft tumor growth and metastasis in vivo." (PMID 38992659, 2024). "This metabolic shift empowers macrophages to overcome the “don’t eat me” signal transmitted by the CD47 molecule on tumor cells." (PMID 38523155, 2024). "For CD47, 10 patients (50%) had high CD47 levels in their tumor, 9 patients (45%) had medium CD47 levels, and 1 patient (5%) had low CD47 levels." (PMID 39627379, 2024). "The antitumor effects of CD47 blockers are dependent on type I IFN signaling and cross-initiation of tumor-associated DCs." (PMID 38564002, 2024). "CD47 acts as a defense mechanism for tumor cells by sending a “don’t eat me” signal via its bond with SIRPα." (PMID 38247566, 2024). "First, using IHC, we identified that the the Foxp1 level was upregulated in the anti-CD47-treated tumor tissues compared to the control group." (PMID 38398223, 2024). "Preclinical models have shown benefit of anti-CD47 antibodies to restore macrophage recognition and phagocytosis of tumor cells, including LMS cell line xenografts." (PMID 38473300, 2024). "The CD38/CD47 BsAbs had a greater ability to block the CD47/SIRPα signal in CD38+/CD47+ tumor cells than IMM01 (SIRPα Fc fusion protein)." (PMID 38983860, 2024). "Recent studies have highlighted the potential of dual-targeting CD47/SIRPα and PD-1/PD-L1 in inhibiting tumor growth." (PMID 38462636, 2024).
tumor (continued). "The κλ body platform was used to generate a human CEACAM5xCD47 BsAb selectively blocking CD47 on CEACAM5-positive tumor cells." (PMID 38720892, 2024). "Lemzoparlimab (TJ011133 or TJC4) is a differentiated anti-CD47 IgG4 antibody that targets a CD47 epitope, which allows a unique red blood cell sparing property while retaining strong anti-tumor activity." (PMID 39697225, 2024). "TTI-621, a SIRPα-hIgG1 Fc fusion protein, selectively promotes macrophage-mediated phagocytosis by binding to CD47 on tumor cells." (PMID 38783333, 2024). "Alternative approaches to interfere with CD47 function involve the use of a SIRPa-Fc fusion protein to bind to and prevent tumor CD47 from engaging SIRP receptors on TAMs." (PMID 39194679, 2024). "Early precursors of CAR-M were the simultaneous blocking of CD47/SIRPα which have been shown to promote phagocytotic activity with high specificity against the tumour antigen." (PMID 38566987, 2024). "While many naturally infiltrating macrophages tend to display anti-inflammatory phenotypes, often manipulated by tumor cells expressing suppressive molecules like CD47 (“don’t eat me”), CAR-macrophages seem to have the ability to overcome these problems." (PMID 37877819, 2024). "CD47 + tumor cells interfere with SIRPα expressed by phagocytes from being phagocytosed and sustaining suppressed immune sensing." (PMID 39696410, 2024). "CD47, a ligand expressed on tumour cells, has also attracted great attention because its interaction with the macrophage receptor SIRPα can regulate macrophage phagocytic capability." (PMID 38303024, 2024). "Lemzoparlimab is an anti-CD47 antibody screened using human-derived natural bacteriophage technology that can specifically target tumor cells to circumvent hematological adverse events by reducing binding to erythrocytes." (PMID 38464520, 2024). "CD47 was mainly expressed in the tumor cell membrane and cytoplasm, and the rate of high CD47 expression was 63.7%." (PMID 38317230, 2024). "Tumor cells often overexpress CD47, which sends a “don’t eat me” signal to macrophages via its interaction with SIRPα." (PMID 39275127, 2024). "Both the nanobody and its derivatives stimulated substantial phagocytosis of MCF7 and U937 tumor cell lines via the primary macrophages ex vivo, thus validating the affinity and functional activity of the derived anti-CD47 nanobody." (PMID 38247566, 2024). "Co-targeting CD47 and angiogenesis successfully controlled tumor neovascularization and led to an immune-favorable, macrophage-infiltrating, pro-inflammatory tumor microenvironment." (PMID 39335665, 2024). "Macrophages that phagocytose tumor cells as a result of anti-CD47 antibody treatment can prime anti-tumor CD8 + T-cell responses, which indicates the role of phagocytic cells in priming the CD8 + T cell response." (PMID 39696410, 2024). "Mice bearing CIN-afflicted tumors with wild-type CD47 levels succumb similar to controls, but long-term survival is maximized by SIRPα blockade on adoptively transferred myeloid cells plus anti-tumor monoclonal IgG." (PMID 38805560, 2024). "Such cells are the initiating effector cells, and survivors make de novo anti-cancer IgG that not only promote phagocytosis of CD47-null cells but also suppress tumor growth." (PMID 38805560, 2024). "CD47 is a ‘don’t eat me’ signal overexpressed on tumor cells and this interacts with its ligand SIRPa, which is a protein expressed on macrophages and dendritic cells, to prevent phagocytosis." (PMID 38533720, 2024). "One such mechanism is the expression of CD47 in tumor cells, which sends a “don’t eat me” signal to the macrophages and, thus, prevents phagocytosis." (PMID 39201801, 2024). "Recent studies suggested that immune checkpoints such as programmed cell death 1-ligand 1 (PD-L1), CD276, and CD47 are upregulated in CSCs, which helps them evade immune surveillance in tumor initiation, progression, and metastasis." (PMID 38699238, 2024).
tumor (continued). "The IF double staining assay demonstrated that the CTLA4 level in the tumor tissues was mainly concentrated in tumor cells after anti-CD47 Ab treatment." (PMID 38398223, 2024). "Crucially, the combination of inhibitors that targeted cancer drivers with anti-CD47 eliminated persister cells in vivo and resulted in tumor regressions and cures in a number of relevant in vivo model systems." (PMID 38690738, 2024). "Higher expression of CD47 on tumor cells thereby functions as a ‘don’t eat me’ signal that prevents their clearance by macrophages and neutrophils and limits the presentation of tumor antigens to cytotoxic T cells by antigen-presenting cells." (PMID 39201643, 2024). "In summary, we have characterized a novel, high-affinity fully human anti-SIRPα antibody that blocks SIRPα–CD47 interactions and promotes macrophage-mediated phagocytosis of tumor cells." (PMID 38319147, 2024). "Blocking the interaction of CD47 with its receptor, SIRPα, on macrophages enables phagocytosis and inhibits tumour progression." (PMID 38183060, 2024). "Our findings showed that the CD38/CD47 BsAbs strongly blocked the CD47/SIRPα interaction in CD38/CD47 double-positive tumor cells, indicating that the inhibition of CD47/SIRPα depended on the engagement of CD38." (PMID 38983860, 2024). "Blockade of the CD47/SIRPa signaling pathway enables macrophage phagocytosis of tumor cells that were otherwise protected." (PMID 38533720, 2024). "This process enhances the tumour CD47 ‘don’t eat me’ signal and induces MET formation, which exerts a crucial role in multiple metastatic stages." (PMID 39025845, 2024). "CD47 is an antiphagocytosis immune checkpoint molecule, which mediates tumor evasion via the CD47/SIRP-α interaction, resulting in a “do not eat me” signal." (PMID 38646934, 2024). "Currently, BsAb and peptide drugs predominantly target both CD47 and PD-1 or PD-L1, resulting in significant inhibition of tumor growth." (PMID 38462636, 2024). "Many are designed to bring immune cells in proximity with tumor cells by targeting both immune markers (CD137/4-1BB, CD27, PD-1, OX-40) and tumor markers (B7-H3, CD47, PD-L1, 5T4, ROR1, claudin, GPC3, HLA-G, PSCA)." (PMID 38254823, 2024). "A recent study demonstrated that a synergic expression of galectin-3 with CD47 in peritoneal metastatic cells is correlated with diffuse-type GC and tumor relapse." (PMID 39519285, 2024). "The findings suggest that the inhibition of CD47 resulted in an anti-tumor response by promoting the polarization of M1 macrophages and enhancing macrophage phagocytosis." (PMID 38532108, 2024). "Here we have shown how SIRPα expressing myeloid cells encounter a CD47-rich microenvironment as they infiltrate the tumor." (PMID 38577107, 2024). "Inhibiting the CD47-SIRPα axis, which acts as an anti-phagocytic signal, has shown promise in preclinical models, leading to increased tumor phagocytosis and reduced tumor burden." (PMID 38732975, 2024). "Applying anti-CD47 mAbs in TOV OC cell lines resulted in inhibition of tumor cell growth—their migration in invasion." (PMID 38892394, 2024). "The A2+/NY+ tumor cell lines Me275, A375, and Saos-2 express CD47 (top), and we observed higher binding (bottom) as well as saturation of binding at lower concentrations for CV1-SiRPα-Fc (CV1-Fc) than wtSiRPα-Fc recombinant fusion proteins." (PMID 38828721, 2024). "Infiltration by large numbers of CD68-IT cells was much more common among patients with a high expression of CD47 in tumor cells." (PMID 39201801, 2024). "In the current study, we found that tumor cell OXPHOS product ATP plays a critical role during CD47-SIRPα ICB." (PMID 38982116, 2024). "In vitro and in vivo studies reveal that the hBisAb exhibits a remarkable selectivity for tumor cells over red blood cells, addressing a common challenge of CD47-targeted therapies by minimizing unwanted hematologic effects." (PMID 38475778, 2024).
tumor (continued). "The selective targeting of tumor cells by anti-CD47 antibodies is based on the interaction between CD47, often overexpressed on cancer cells, and signal regulatory protein alpha (SIRPα) on phagocytic cells." (PMID 39682299, 2024). "Anti-CD47 treatment of mice harboring orthotopically injected luciferase-expressing GBM xenografts resulted in an almost complete inhibition of tumor growth as measured by bioluminescence photon flux." (PMID 39194679, 2024). "CD47 blockade enhances antigen presentation, phagocytosis, and immune infiltration in various tumor models, supporting the development of CD47 blockade immunotherapy agents." (PMID 38475778, 2024). "CD47 × PD‐L1 BisAb treatment of C57BL/6 mice inoculated with AT3‐OVA resulted in a significant reduction in tumor volume compared to mice treated with an isotype control antibody." (PMID 39584189, 2024). "The CD47 protein functions as a negative regulator of the cytotoxic T-cell response against cancer cells, potentially contributing to tumor progression." (PMID 39594611, 2024). "Increased expression of CD47 on the surface of tumor cells enables them to evade phagocytosis, thereby facilitating tumor growth and progression." (PMID 39682556, 2024). "CD47-overexpresing SC262 cells were generated, and these cells can evade killing by NK cells and macrophages by triggering the CD47-SIRPα "don’t eat me" signaling pathway and ultimately elicit robust tumor control in vitro and in vivo." (PMID 38711046, 2024). "Another interesting target is CD47, a transmembrane-bound protein highly expressed in some tumor cells, including angiosarcomas." (PMID 38279265, 2024). "In solid tumors, the formidable anti-tumor impact resulting from blocking the “don’t eat me” signal, arising from CD47–SIRPα interaction, is constrained, especially compared to its efficacy in hematopoietic malignancies." (PMID 38398223, 2024). "CD47 is a transmembrane glycoprotein that is highly expressed by tumor cells, enabling them to evade immune surveillance mediated by macrophages through the CD47-SIRPα complex." (PMID 38429732, 2024). "When considering changes in individual patients, most patients (81.5%) demonstrated decreasing tumor CD47 expression post NACT." (PMID 39138571, 2024). "Here the authors show that, by reprograming tumor cell metabolism toward OXPHOS for ATP production, tumor cell-intrinsic type I IFN signaling is required for CD47-SIRPa blockade efficacy." (PMID 38982116, 2024). "By combining the chemotherapeutic action of DOX with the blockade of CD47, this strategy effectively reverses the tumor’s defense against immune clearance, leading to enhanced anti-tumor activity." (PMID 39334825, 2024). "Macrophagesare an important component of the OvCa tumor microenvironment andare manipulated to aid in cancer progression via CD47-SIRPαsignaling." (PMID 38558434, 2024). "We demonstrate these tumor cells are rapidly phagocytosed in vitro when co‐cultured with murine macrophages treated with commercially available anti‐CD47 monoclonal antibodies (mAbs)." (PMID 39553428, 2024). "Our phagocytosis assays show that NextA treatment increases phagocytosis of tumor cells by macrophages, which was further enhanced with anti-CD47." (PMID 38414061, 2024). "ISB 1442 induced prominent phagocytosis of tumor cells, suggesting that CD47 inhibition was sufficient to enable macrophages to engulf multiple tumor cells in vitro." (PMID 38448430, 2024). "The combined activity of reprogramming macrophages from M2 to M1 polarization and blocking CD47-SIRPa signaling stimulates macrophage phagocytosis and killing of tumor cells." (PMID 39627379, 2024). "Here, we find that lactate generated by both tumor and immune cells in the microenvironment increases the expression of CD47 and activation of STAT3 in association with reduced microglial/macrophage phagocytosis of tumor cells." (PMID 39545414, 2024).